ELN (elastin)
Diseases named in the same sentence as ELN in open-access papers (continued):
Sharing a sentence is not in itself a finding about the gene and the disease.
colorectal cancer (13 papers, 2020 to 2026). A primary or metastatic malignant neoplasm that affects the colon or rectum. "Increased elastin expression was associated with increased colorectal cancer progression, and the mechanism could be through the induction of EMT." (PMID 34359550, 2021). "ELN was predicted to have overexpression in colorectal cancer but was under-expressed in the majority of the other types, while LGALS8 was found to be downregulated in colorectal cancer and overexpressed in all other types." (PMID 38544823, 2024). "The expression level of the ELN gene was found to be elevated in colorectal cancer patients, suggesting that ELN could have triggered EMT." (PMID 37441420, 2023). "The weighting could be adjusted by the required ancillary testing (e.g., MSI testing in endometrial cancer)/ancillary testing recommended by consensus statements (elastin staining to assess for lymphatic invasion/vascular invasion in colorectal cancer resections)." (PMID 34185808, 2021). "ELN has also been shown to regulate tumor development and the tumor microenvironment (TME) in colorectal cancer." (PMID 37061682, 2023). "In colorectal cancer (CRC), elastin gene expression was recently examined and it was found that elastin decisively regulates tumor development and the microenvironment." (PMID 34827210, 2021). "Studies have reported that elastin, a ferroptosis inducer, could irreversibly inhibit SLC7A11 and synergize with cisplatin to increase the drug’s cytotoxicity, and that the blocking of SLC7A11 effectively increased the intracellular level and cytotoxicity of cisplatin in colorectal cancer." (PMID 34790572, 2021). "Although the role of elastin in MIBC EMT has not been extensively studied, elastin has been shown to play a significant role in colorectal cancer EMT." (PMID 34359550, 2021).
idiopathic pulmonary fibrosis (12 papers, 2013 to 2025). Idiopathic pulmonary fibrosis (IPF) is a nonneoplastic pulmonary disease that is characterized by the formation of scar tissue within the lungs in the absence of any known cause. "Usual interstitial pneumonia (UIP) is the histopathology underlying IPF and is characterized by heterogeneity of disease and accumulation of fibroblast foci and collagen with an emphasis on collagen type I (col1) over type III (col3), and abnormalities in other matrix molecules including elastin." (PMID 26013144, 2015). "Particularly, idiopathic pulmonary fibrosis (IPF) is characterized by excessive deposition of extracellular matrix molecules, such as collagen and elastin, with overactivation of fibroblasts/myofibroblasts." (PMID 35814272, 2022).
lung carcinoma (12 papers, 2014 to 2025). "Interestingly, high expression of DCN, LAMA2, and ELN in lung cancer is associated with better survival." (PMID 37848457, 2023). "For example, neutrophil elastin (NE) was shown to indirectly promote the tumor growth by stimulating the PI3K signaling pathways in lung cancer cells." (PMID 30689655, 2019). "Typically, this structure is best visualized with a special elastin stain and is used to stage pleural invasion in lung carcinomas." (PMID 27788264, 2016). "Mean levels of NE-generated elastin were 510% higher in serum from patients diagnosed with lung cancer (12.6 nM) than in controls (2.1 nM p < 0.0001)." (PMID 25935650, 2015). "Elevated levels of NE have been coupled with cancer invasion and metastasis in lung cancer and most likely explains the increased levels of NE-generated elastin fragments in lung cancer patients." (PMID 25935650, 2015). "We selected unique fragments of elastin degraded specifically by NE, developed a novel ELISA assay detecting exclusively NE-degraded elastin and investigated NE activity towards elastin in lung cancer and IPF." (PMID 25935650, 2015). "High NE proteolytic activity on elastin may therefore be related to the excessive ECM turnover observed during the progression of lung cancer." (PMID 25935650, 2015). "Serum levels of NE-degraded elastin might be used to detect excessive lung tissue degradation in lung cancer and IPF." (PMID 25935650, 2015). "To investigate these changes in lung cancer, we analyzed both collagen (SHG) and elastin (TPEF) in the same FOV of healthy and tumor-affected tissues for each patient." (PMID 40895158, 2025). "The quantitative analysis of NE-degraded elastin by EL-NE assay showed that the levels of NE-degraded elastin in the serum of patients with IPF and lung cancer were significantly higher than those in healthy controls." (PMID 34327245, 2021). "Serum levels of NE-generated elastin fragments were significantly increased in patients with IPF (137%, p = 0.002) and in patients with lung cancer (510%, p < 0.001) compared with age- and sex-matched controls." (PMID 25935650, 2015). "The EL-NE antibody was selected due to its high reactivity towards free peptide, elastin cleaved with NE and serum from patients diagnosed with IPF and lung cancer, combined with a low reactivity towards the elongated peptide, intact elastin as well as elastin cleaved with MMPs." (PMID 25935650, 2015). "Reports have demonstrated that excess NE released by neutrophils in lung cancer promotes the invasion and metastasis of cancer cells by destroying the intrinsic tissue barrier composed of the basement membrane and other ECM components (including elastin, collagen, and proteoglycan)." (PMID 34327245, 2021). "The mechanism and function of RNASE7, and ELN had not been reported in lung cancer." (PMID 32699529, 2020).
arteriopathy (11 papers, 2011 to 2025). "Similarly, specific anatomic features such as coronary ostial abnormalities and biventricular outflow obstruction place patients with elastin arteriopathy (including those with WBS) at risk for sudden death, requiring cautious anesthetic management." (PMID 29523523, 2018). "Elastin (ELN) haploinsufficiency in WBS results in an arteriopathy involving medium- and large-sized arteries leading to lumen narrowing." (PMID 35765027, 2022). "Mainly due to Elastin (ELN) deficiency, WBS patients show a generalized arteriopathy characterized by hypertrophy of smooth muscle cells, increased number and disorganized lamellar structures, and fragmented elastic fibers." (PMID 29554110, 2018). "The mid abdominal aorta showed lesions suggestive of a systemic elastin arteriopathy." (PMID 32926466, 2020). "While interactions of ELN variation with genetic variation in other 7q11.23 genes, and throughout the genome, undoubtedly impact expression of arteriopathy, our results support the use of the method developed here to uncover genotype-phenotype links in individuals with CNVs." (PMID 29614955, 2018). "Nutritional supplements such as β-aminopropionitrile (contained in certain legumes), dill extract, and tannic acid may also be effective in preventing elastin arteriopathy." (PMID 26384008, 2015). "Next, testing for effects of ELN rs2528795 SNP in both WS and Dup7, we found the interaction of diagnosis and rs2528795 genotype significantly predicted participants’ cardiovascular status, explaining over one-third of the variance in arteriopathy (Nagelkerke’s R2 = 0.351, p < 0.021)." (PMID 29614955, 2018). "Therefore, this feature is considered a generalized elastin arteriopathy that presents in WS." (PMID 26384008, 2015). "However, the relation of elastin and human arterial disease is complex and incompletely understood." (PMID 21647416, 2011).
Pseudoxanthoma elasticum (11 papers, 2013 to 2025). "It has been shown pseudoxanthoma elasticum patients had higher desmosine serum content than controls associated with increased ankle brachial index but not correlated to calcification score, indicating development of peripheral artery disease in these patients is linked to elastin degradation." (PMID 37001705, 2023). "Mutations in the human ABCC6/MRP6 gene is a known cause of pseudoxanthoma elasticum (PXE), a heritable recessive disorder characterized by calcification of elastin fibers in connective tissue, including the heart, vasculature, skin and eyes." (PMID 25893161, 2015). "Pseudoxanthoma elasticum (PXE) is a monogenetic disorder in which mutations in the ABCC6 gene result in calcification and fragmentation of elastin fibers in the skin, the Bruch’s membrane of the eyes, and the internal elastic lamina of the peripheral arteries." (PMID 32859086, 2020). "Pseudoxanthoma elasticum (PXE) is a genetic disease characterized by the calcification of elastin fibers." (PMID 32397252, 2020). "Pseudoxanthoma elasticum (PXE) is a rare and heterogeneous hereditary disorder, characterized by frail and fragmented elastin fibers, with calcium deposits." (PMID 23365766, 2013). "Pseudoxanthoma elasticum (PXE) is a rare hereditary disorder of elastin fibers, characterized by yellowish coalescent papules in flexural surfaces with abnormally lax and corrugated skin." (PMID 23365766, 2013). "Absence of ABCC6 causes pseudoxanthoma elasticum (PXE), an autosomal recessive metabolic disorder characterized by ectopic mineralization in elastin-rich tissues such as the eyes, blood vessel walls, and the skin." (PMID 35186933, 2022). "Pseudoxanthoma elasticum (PXE, OMIM#264800) is a rare autosomal recessive connective tissue disorder characterized by ectopic mineralization and fragmentation of elastin fibers." (PMID 32372237, 2020). "Pseudoxanthoma elasticum (PXE, OMIM 264800) is a rare autosomal recessive disorder with ectopic mineralization and fragmentation of elastin fibers." (PMID 32372237, 2020). "Pseudoxanthoma elasticum (PXE) results in extensive fragmentation and calcification of elastin fibers in the peripheral arteries, which results in peripheral arterial disease (PAD)." (PMID 32859086, 2020).
aortic stenosis (10 papers, 2012 to 2026). Aortic valve stenosis is a aortic valve disease caused by the incomplete opening of the aortic valve. "ELN mutations are commonly associated with aortic stenosis, predominately supravalvar, but other defects associated with it include tetralogy of Fallot, ASD, PS, BAV and VSD." (PMID 39556044, 2025). "For instance, the ELN gene, being a part of WBS deletion, encodes the protein elastin, a component of vascular walls, and its insufficiency leads to aortic stenosis." (PMID 35782865, 2022). "We found that in the context of Dup7, the G allele of rs2528795 in ELN is protective against aortic dilation, but in the context of WS, the same allele increases risk of aortic stenosis." (PMID 29614955, 2018). "The G allele of SNP rs2528795 in the ELN gene was associated with aortic stenosis in WS participants (p < 0.0049) while the A allele of the same SNP was associated with aortic dilation in Dup7." (PMID 29614955, 2018). "Additionally, previous investigations of partial elastin deficiency in which Eln–/– mice express human elastin showed that impaired outward growth contributes to aortic stenosis." (PMID 34990407, 2022). "The predominance of cardiovascular defects (36.4%) in our cohort, including aortic stenosis and PLSVC, reinforces the crucial role of ELN (OMIM #130160) haploinsufficiency in vascular development." (PMID 41494975, 2026).
Arterial stenosis (10 papers, 2012 to 2025). Narrowing or constriction of the inner surface (lumen) of an artery. "The main clinical phenotypes of patients with ELN mutations are arterial stenosis, especially SVAS and pulmonary artery stenosis." (PMID 36518217, 2022). "The study also illustrates the importance of screening for ELN gene mutations in patients with arterial stenosis, especially SVAS and pulmonary stenosis, in order to identify the genetic etiology involved." (PMID 36518217, 2022). "The deletion of the ELN gene is presumed to be the main cause of arterial stenosis." (PMID 32239321, 2020). "Elastin haploinsufficiency could also cause hyperplasia of sub-endothelial migration and vascular smooth muscle cell, leading to encroachment on the vascular lumen and arterial stenosis." (PMID 37422671, 2023). "We identified a de novo nonsense mutation in the ELN gene leading to mild SVAS and severe branch pulmonary artery stenosis." (PMID 37980465, 2023). "To date, deletion of the elastin (ELN) gene has been identified as the main cause of cardiovascular disorders in WBS patients, especially arterial stenosis." (PMID 35379245, 2022).
pelvic organ prolapse (10 papers, 2013 to 2025). Abnormal descent of a pelvic organ resulting in the protrusion of the organ beyond its normal anatomical confines. "Pathogenic elastin remodeling can also occur in vaginal tissues post-childbirth and is linked to the development of pelvic organ prolapse." (PMID 37001705, 2023). "In previous studies, mice deficient in the LOXL1 gene showed reduced elastin content in multiple tissues leading to pelvic organ prolapse, emphysematous changes, and vascular abnormalities." (PMID 23441117, 2013). "MMP-1, -2 and -9 not only degrade collagen but also other components of the extracellular matrix in particular elastin, proteoglycan at the base of the remodeling of this matrix, characteristic of pelvic organ prolapse." (PMID 40607267, 2025). "The downregulation of LOXL1 expression resulted in the inability of mice to synthesize elastic fibers normally after childbirth, leading to postnatal pelvic organ prolapse and concomitant pro-elastin accumulation." (PMID 38217541, 2024). "Fibulin-3 knockout mice have reduced fascial elastin resulting in inguinal hernia and pelvic organ prolapse development." (PMID 37001705, 2023). "A comparison of ECM composition between healthy vaginal tissues and the stiffer pelvic organ prolapse tissue revealed that the prolapsed tissue contained 30% more collagen and 91% more elastin protein compared to the healthy tissue." (PMID 36772084, 2023). "This study investigates the effect of local oestrogen therapy (LET) on the expression of proteins participating in collagen/elastin biogenesis and immune markers in vaginal tissues of post‐menopausal women with severe pelvic organ prolapse (POP)." (PMID 30772947, 2019). "There appears to be a potential correlation between the reduced expression of elastin and the severity of pelvic organ prolapse in women, suggesting that elastin may have a specific role in the development of this dysfunction." (PMID 38674297, 2024). "The ECMs derived from women with pelvic organ prolapse (POP) that were used in this study seem to have the characteristics of scar tissues, since they were stiffer than healthy controls and had higher ECM protein content (collagen and elastin)." (PMID 32635512, 2020).
aging (9 papers, 2016 to 2025). A developmental process that is a deterioration and loss of function over time. "Similar to facial skin, neck skin aging is influenced by both intrinsic and extrinsic factors that promote loss of skin elasticity and further wrinkle formation, resulting from the gradual degradation of collagen and elastin." (PMID 41215693, 2025). "Skin aging is characterized by the degradation of the extracellular matrix (ECM), with loss of elasticity due to the breakdown of fibers such as collagen and elastin and the decrease in fibroblasts." (PMID 39859067, 2025). "ROS generated by skin aging can facilitate the degradation of collagen and elastin through the activation of the mitogen-activated protein kinase (MAPK) signaling pathway, thereby contributing to the process of skin aging." (PMID 40969599, 2025). "Alterations in collagen and elastin of the extra cellular matrix (ECM) are primarily responsible for the clinical manifestations of skin aging such as wrinkles, sagging, and laxity." (PMID 27483310, 2016). "In addition, excessive ROS induces collagen and elastin chain cleavage, which worsens skin aging." (PMID 39334769, 2024). "Activated MMPs may degrade collagen, elastin and other ECM, probably resulting in skin aging." (PMID 38246969, 2024).
Aortic dissection (9 papers, 2006 to 2024). Aortic dissection refers to a tear in the intimal layer of the aorta causing a separation between the intima and the medial layers of the aorta. "Mutations in genes that contribute to the elastin contractile unit have also been associated with aortic dissection." (PMID 37894894, 2023). "Increased ascending aorta diameter is associated with reduced elastin density and increased collagen density, which has a profound impact on aortic dissection." (PMID 34336095, 2021). "Age-related elastin fragmentation and medial degeneration are the hallmarks of aortic stiffness leading to aortic dissection, which presumably explains the parallel loss of fibulin-1." (PMID 29867203, 2018). "Furthermore, we checked whether the predisposition to aortic dissection could be explained by malfunctioning elastin contractile units." (PMID 37894894, 2023). "This increased production of MMPs is expected to result in the degradation of elastin and collagen, which are structural components of the media, making the aortic wall vulnerable and prone to aortic dissection." (PMID 39471491, 2024). "VVG staining of suprarenal aortas showed severe lamina elastin degradation and evident hematoma formation in WT aortas but such pathological features of aortic dissection were barely observed in KO mice." (PMID 33667992, 2021). "Recent clinical and experimental studies have revealed that aortic dissection is mediated by inflammation in the adventitia and media of the aorta, leading to degradation of the extracellular matrix, including elastin, and tearing in the medial layer." (PMID 23843799, 2013). "Several genes that encode for extracellular matrix components such as collagen IV α2 and -α5, collagen VI α3, collagen XIV α1, collagen XVIII α1 and elastin were down-regulated in aortic dissection, whereas levels of matrix metalloproteinases-11, -14 and -19 were increased." (PMID 16824202, 2006). "As one of the main pathological features of the aortic media in aortic dissection is elastin lamellar disruption, elastin degradation products (sELAF) could potentially be released into the circulation at the time of aortic dissection, which may reflect the damage of vascular media." (PMID 35358189, 2022).
arteriosclerosis (9 papers, 2012 to 2025). A vascular disorder characterized by thickening and hardening of the walls of the arteries. "A key characteristic of arteriosclerosis is the loss of elastin fibers, which are replaced by collagen in the vessel tunica media, resulting in decreased elasticity." (PMID 40283075, 2025). "Arteriosclerosis in CKD affects large vessels with reduced elastin and increased collagen in the medial layer, calcification, and hypertrophy of vascular smooth muscle cells." (PMID 35773282, 2022). "Continuous stresses on elastin fibers induce fragmentation and reduction in the vessel wall, and aging makes the aorta more tortuous through a process known as arteriosclerosis." (PMID 31415390, 2019). "Renal failure and ageing are two of the main determinants of the arteriosclerosis characterized by direct structural changes including elastin fragmentation and medial calcification that increased the arterial stiffness." (PMID 31635248, 2019). "PWV is now largely considered a measure of arteriosclerosis (i.e., an outside-in process related to structural changes in the adventitial and medial layers from calcification, glycation, elastin fragmentation and degradation, and collagen undulation/deposition and cross-linking)." (PMID 36701358, 2023).